PIK3C3 (phosphatidylinositol 3-kinase catalytic subunit type 3)
Diseases named in the same sentence as PIK3C3 in open-access papers (continued):
Sharing a sentence is not in itself a finding about the gene and the disease.
cataract (4 papers, 2016 to 2023). Partial or complete opacity of the crystalline lens of one or both eyes that decreases visual acuity and eventually results in blindness. "Tissue-specific knockout of autophagy-related genes Atg5 and Pik3c3 in the lens causes cataracts." (PMID 27294265, 2016). "Studies on lens-specific Atg5−/− mice and Pik3c3/Vps34−/− mice have discovered that impaired autophagy in lenses generates cataracts." (PMID 35954230, 2022). "A similar effect occurs upon pik3c3/vps34 deletion in LECs, which also leads to age‐dependent cataracts." (PMID 34459017, 2021). "The deletion of Atg5 in mice has been associated with age-related cataracts and the deletion of Pik3C3 with congenital cataracts in mice, although neither deletion alone appeared to affect organelle degradation, and neither molecule has been associated with cataracts in humans." (PMID 36766820, 2023).
COVID-19 (3 papers, 2021 to 2025). A disease caused by infection with severe acute respiratory syndrome coronavirus 2. "It was found that transcript levels of key factors promoting autophagy, i.e. ULK-1, ATG5, UVRAG, AMBRA, PIK3C3, and LC3, are significantly reduced in mononuclear cells of COVID-19 patients compared to healthy controls, and the phenomenon was more pronounced in severe COVID-19 patients." (PMID 33692788, 2021).
esophageal squamous cell carcinoma (3 papers, 2020 to 2022). Esophageal squamous cell carcinoma (ESCC) is a type of esophageal carcinoma (EC) that can affect any part of the esophagus, but is usually located in the upper or middle third. "In a series of 31 pairs of normal and esophageal SCC tissues, PIK3C3 mRNA levels were significantly lower in esophageal SCC tissues." (PMID 34681622, 2021). "In a study using KYSE-150 and TE-12 esophageal SCC cells, PIK3C3 overexpression suppressed cancer cell proliferation." (PMID 34681622, 2021). "In contrast, esophageal SCC patients with low PIK3C3 protein levels exhibited a worse prognosis than those patients with high PIK3C3 levels." (PMID 34681622, 2021). "Although most studies revealed a positive correlation between PIK3C3 and cell proliferation and growth, one in vitro study of esophageal SCC showed the opposite results." (PMID 34681622, 2021). "On the other hand, polymorphisms on VPS34/PIK3C3 do correlate with increased cancer risk, specifically in pancreatic adenocarcinoma and esophageal squamous cell carcinoma." (PMID 33147747, 2020).
neuroblastoma (3 papers, 2015 to 2023). Neuroblastoma (NB) is the most common solid, extracranial childhood tumor. "The inhibition of PIK3C3-dependent autophagy could prevent neuroblastoma cell apoptosis and necrosis through oxidative stress." (PMID 35629298, 2022).
prostate carcinoma (3 papers, 2018 to 2022). A carcinoma that arises from epithelial cells of the prostate gland. "Similarly, it has been reported that the protein level of Bif-1, an autophagy effecter involved in autophagosome biogenesis as part of the PIK3C3/VPS34 complex, was decreased in gastric and prostate cancers, and Bif-1 knockout mice are prone to tumorigenesis." (PMID 30572663, 2018). "Although PIK3C3/PIK3R4 mutation and PIK3C3 gene amplification are infrequent events in prostate cancer (<1% of cases), PIK3R4 high-level gene amplification is observed in up to 6.5% of cases and could potentially facilitate prostate cancer growth." (PMID 32630372, 2020).
Alzheimer disease (2 papers, 2020 to 2021). A progressive, neurodegenerative disease characterized by loss of function and death of nerve cells in several areas of the brain leading to loss of cognitive function such as memory and language. "The expression levels of NRBF2, along with BECN1, PIK3C3 and PIK3R4, are reduced in Alzheimer disease (AD) post mortem brains." (PMID 33459128, 2021).
cervical cancer (2 papers, 2018 to 2020). A primary or metastatic malignant neoplasm involving the cervix. "Autophagy mediates enhanced AMPK activity in human breast and cervical cancer cells and activated AMPK initiate autophagosome formation by activating PIK3C3/VPS34 complex or by inhibiting mTOR and regulate ERK1/2." (PMID 32184774, 2020).
chronic obstructive pulmonary disease (2 papers, 2023 to 2024). A chronic and progressive lung disorder characterized by the loss of elasticity of the bronchial tree and the air sacs, destruction of the air sacs wall, thickening of the bronchial wall, and mucous accumulation in the bronchial tree. "Another study demonstrated that inhibition of SPP1 blocked the PIK3C3-AKT-mTOR pathway, resulting in the alleviation of chronic inflammation and mediating Th17/Treg differentiation in chronic obstructive pulmonary disease (COPD)." (PMID 38919629, 2024).
endometrial carcinoma (2 papers, 2021 to 2024). A malignant tumor arising from the epithelium that lines the cavity of the uterine body. "In contrast, PIK3C3 levels were decreased in high tumor stages of renal clear cell carcinoma, endometrial carcinoma, thyroid carcinoma, and mesothelioma." (PMID 34681622, 2021). "On the other hand, PIK3C3 RNA was significantly downregulated in colon and rectum adenocarcinoma, breast invasive carcinoma, renal cell carcinoma (RCC), prostate adenocarcinoma, thyroid carcinoma, and endometrial carcinoma." (PMID 34681622, 2021).
esophageal cancer (2 papers, 2014 to 2019). A primary or metastatic malignant neoplasm involving the esophagus. "Even in esophageal cancer tissues, there is a strong correlation between overexpression of GAPDH and upregulation of autophagy-related genes, like ATG12 and PIK3C3 (phosphatidylinositol 3-kinase catalytic subunit type 3)." (PMID 31027346, 2019).
gastric adenocarcinoma (2 papers, 2020 to 2021). "Significantly upregulated PIK3C3 RNA expression was observed in HCC, cholangiocarcinoma, gastric adenocarcinoma, and SCC of the lung, head, and neck versus the corresponding normal controls." (PMID 34681622, 2021). "PIK3C3 RNA levels were increased in high versus low tumor stages of HCC, gastric adenocarcinoma, and uterine carcinosarcoma." (PMID 34681622, 2021).
Insulin resistance (2 papers, 2017 to 2018). Increased resistance towards insulin, that is, diminished effectiveness of insulin in reducing blood glucose levels. "Additionally, Pik3c3 mutants were less resistant to insulin as homeostasis model of insulin resistance (HOMA-IR) were significantly reduced." (PMID 29695642, 2018).
ZIKV infection (2 papers, 2020). "Interestingly, immune escape by ZIKV infection could be caused by downregulation of prolactin signaling including IRS2, PIK3C3, JAK3, STAT3, and IRF1 as well as mitochondria dysfunction and oxidative phosphorylation in myeloid dendritic cells." (PMID 32287277, 2020). "Interestingly, phosphatidylinositol 3-kinase catalytic subunit type 3 was upregulated at 48h p.i., while phosphatidylinositol 3-kinase regulatory subunit beta was downregulated, suggesting that the PI3K/A cascade is activated following ZIKV infection." (PMID 32817655, 2020).
age (1 paper, 2017). A temporal measurement of the time period elapsed since an identifiable point in the life cycle of an organism. "The loss of lens-specific autophagy-related 5 (Atg5) has been reported to result in age-related cataract formation, and Pik3c3/Vps34 genes are shown to leading cortical cataract in lens." (PMID 28083623, 2017).
Anxiety (1 paper, 2022). Intense feelings of nervousness, tension, or panic often arise in response to interpersonal stresses. "The sixth behavioral trait, number of fecal boli, is the only anxiety-related trait mapping to a significant locus on chromosome 18 within which the Pik3c3 gene is located." (PMID 36712851, 2022).
Azoospermia (1 paper, 2025). Absence of any measurable level of sperm,whereby spermatozoa cannot be observed even after centrifugation of the semen pellet. "As a key autophagy-related gene, PIK3C3 was observed to be upregulated in Sertoli cells of non-obstructive azoospermia (NOA) patients." (PMID 40884870, 2025).
hyperparathyroidism (1 paper, 2024). Hyperfunction of the parathyroid glands resulting in the overproduction of parathyroid hormone. "This consistency suggests a correlation between elevated expression of PIK3C3 and decreased expression of SLC40A1 with an increased risk of hyperparathyroidism." (PMID 38499600, 2024). "Genetically predicted expression of IGSF11, PIK3C3, and SLC40A1 retained significant associations with hyperparathyroidism risk in GTEx thyroid tissue cohort (P < 1.25e−02, inverse-variance weighted methods)." (PMID 38499600, 2024). "Genetically predicted expression of CMKLR1, PIK3C3, and SLC40A1 retained significant causal associations with hyperparathyroidism risk in GTEx whole blood samples (P < 1.25e−02, inverse-variance weighted methods)." (PMID 38499600, 2024). "Five drug targets (CMKLR1, FSTL1, IGSF11, PIK3C3 and SLC40A1) showed significant causation with hyperparathyroidism in both eQTLGen and GTEx cohorts by MR analysis." (PMID 38499600, 2024). "Additionally, clinical trials are imperative to evaluate the efficacy and safety of targeting PIK3C3 or SLC40A1 for therapeutic management of hyperparathyroidism." (PMID 38499600, 2024). "Moreover, the association between PIK3C3 and SLC40A1 with hyperparathyroidism was corroborated using a parallel analysis in the GTEx database, reinforcing the credibility of the potential drug targets identified in this investigation." (PMID 38499600, 2024). "Targeting PIK3C3 and SLC40A1 may offer effective novel pharmacotherapies for impeding hyperparathyroidism progression and reducing disease risk." (PMID 38499600, 2024). "Consequently, we were unable to validate whether protein levels of PIK3C3 and SLC40A1 consistently associated with hyperparathyroidism risk." (PMID 38499600, 2024). "Consequently, antagonists of PIK3C3 and protagonists of SLC40A1, may represent a novel and robust strategy for reducing the risk of hyperparathyroidism." (PMID 38499600, 2024). "In summary, this cis-eQTL-wide Mendelian randomization and colocalization analysis identified PIK3C3 inhibitors and SLC40A1 antagonists as promising therapeutic targets for hyperparathyroidism." (PMID 38499600, 2024). "This study identifies PIK3C3 and SLC40A1 as potential genetically proxied druggable genes and promising therapeutic targets for hyperparathyroidism." (PMID 38499600, 2024).
liver diseases (1 paper, 2022). "The construction of PIK3C3 transgenic pigs may provide a new experimental animal resource for PIK3C3 function studies in liver diseases." (PMID 35629298, 2022). "These genetically engineered Diannan miniature pigs may provide a new experimental animal resource for the functional study of PIK3C3 in liver diseases." (PMID 35629298, 2022). "Therefore, the construction of PIK3C3 transgenic pigs may provide a new experimental animal resource for liver diseases." (PMID 35629298, 2022).
pulmonary fibrosis (1 paper, 2024). Chronic progressive interstitial lung disorder characterized by the replacement of the lung tissue by connective tissue, leading to progressive dyspnea, respiratory failure, or right heart failure. "Although PIK3C3 inhibition has proven beneficial in kidney fibrosis, the therapeutic effects of PIK-III in dermal or pulmonary fibrosis remain to be elucidated." (PMID 39240940, 2024). "However, a pharmacological inhibitor of PIK3C3, PIK-III, but not SAR405 or autophinib, demonstrated anti-fibrotic effects in dermal and lung fibroblasts as well as in animal models of skin and lung fibrosis." (PMID 39240940, 2024).
renal clear cell carcinoma (1 paper, 2021). "PIK3C3 RNA levels were higher in grade 2–4 head and neck SCC samples but lower in grade 3 and 4 renal clear cell carcinoma samples than in grade 1 samples for each cancer." (PMID 34681622, 2021).
rosacea (1 paper, 2023). A chronic erythematous skin disorder that affects the face. "The expression of autophagy-related genes (ATG9A, ATG10, ATG12, and PIK3C3) was evidently decreased in rosacea lesions compared with normal skin tissues in the GSE65914 dataset." (PMID 36937834, 2023).
shigellosis (1 paper, 2025). Shigellosis is a bacterial infection leading to dysentery and is caused by Shigella, which are small, ubiquitous Gram-negative bacteria belonging to the enterobacteria family. "Finally, we showed that PIK3C3 inhibition decreased S. flexneri dissemination in the infant rabbit model of shigellosis." (PMID 40378153, 2025). "Our work suggests that inhibitors of PIK3C3 may represent novel avenues of therapeutic intervention in shigellosis." (PMID 40378153, 2025). "Finally, we show that inhibiting PIK3C3 attenuated S. flexneri spread in vivo in the infant rabbit model of shigellosis." (PMID 40378153, 2025).
tumor (79 papers, 2011 to 2026). "As a member of the class III phosphoinositide 3-kinase (PI3K) family, PIK3C3 plays a critical role in the regulation of autophagy, and its mutation may disrupt metabolic homeostasis in tumor cells, potentially offering a novel avenue for targeted therapy." (PMID 40919162, 2025). "Notably, molecular analysis identified a somatic PIK3C3 mutation, suggesting a possible link to tumor angiogenesis and providing a rationale for anti-angiogenic therapy." (PMID 40919162, 2025). "Our study further showed that Pik3c3-deficiency in CD8+ T cells has limited effects on clearing tumor metastases, although its underlying mechanisms remain unclear." (PMID 32382030, 2020). "Thus, attempts to improve the XPC photosensitive and deficient repair phenotype using PIK3C3 inhibitors could pave a way for new therapeutic approaches delaying or preventing tumor initiation." (PMID 39562566, 2024). "Preclinical studies have shown that targeting PIK3C3 has anti-tumor activity in breast, colorectal and prostate cancer." (PMID 36010585, 2022). "In another study using an MCF-7 breast cancer cell model, PIK3C3 was observed to stimulate ERK pathway-related tumor progression through the protein kinase-mediated activation of p62." (PMID 35629298, 2022). "Compared to controls, NIH3T3 fibroblasts stably expressing PIK3C3-H868R showed enhanced PIK3C3 lipid kinase activity and increased cell growth in vitro and increased tumor formation in mice." (PMID 34681622, 2021). "Most studies have shown that PIK3C3 inhibitors can repress tumor growth and synergize with various anticancer drugs." (PMID 34681622, 2021). "Altogether, PIK3C3 is a potential therapeutic target for cancer, and targeting agents should be designed with the tumor microenvironment and specific cancer type in mind." (PMID 34681622, 2021). "Knocking down PIK3C3 in mouse embryonal fibroblasts suppressed tumor growth in a xenograft model of tuberous sclerosis complex." (PMID 34681622, 2021). "The histopathological evaluation of tumor sections revealed the development of fibrosarcoma, supporting the role of PIK3C3 in regulating oncogenic transformation." (PMID 34681622, 2021). "The tumor suppressor genes PIK3C3 on chr18q12.3 and SMAD2 on chr18q21.1, which affected the TGF-β pathway, were reported to be related to metastasis." (PMID 29169336, 2017). "Further, Beclin1 is identified as tumor suppressor, which is proved to activate lipid kinase PIK3C3 to accumulate ATG, contributing to autophagy." (PMID 29212196, 2017). "Spatial analysis confirms the co-localization of ZBED6 and PIK3C3 in tumor tissues." (PMID 41858898, 2026). "PIK3C3 is a regulator of autophagy and, in addition, could induce oncogenic transformation and enhance tumor cell proliferation, growth, and invasion through mechanisms independent of autophagy." (PMID 40340749, 2025). "For instance, miR-338-5p is often highly expressed in the more malignant CRC phenotype, implying that it could serve as a promising potential biomarker for CRC diagnosis; it inhibits PIK3C3 and suppresses autophagy to promote tumor invasion and migration." (PMID 36172152, 2022). "In addition, PIK3C3 has been confirmed to regulate tumor cell proliferation by inducing autophagy and regulating iron metabolism." (PMID 36010585, 2022). "PIK3C3 promotes proliferation and tumor growth in various cancer models." (PMID 34681622, 2021). "PIK3C3 protein levels in HCC tissues were positively correlated with tumor stage." (PMID 34681622, 2021). "SAR405, a selective PIK3C3/Vps34 inhibitor, can prevent the formation of late endosome and lysosome compartments by inhibiting the activity of PIK3C3 kinase and can suppress autophagy and mTOR signaling synergistically in tumor cells." (PMID 34895252, 2021).